CENATAC (centrosomal AT-AC splicing factor)
Description:
Component of the minor spliceosome that promotes splicing of a specific, rare minor intron subtype. Negative regulator of centrosome duplication. Constrains centriole number by modulating the degradation of the centrosome-duplication-associated protein SASS6 in an acetylation-dependent manner. SIRT1 deacetylates CENATAC in G1 phase, allowing for SASS6 accumulation on the centrosome and subsequent procentriole assembly. The CENATAC acetylation level is restored in mitosis by NAT10, promoting SASS6 proteasome degradation by facilitating SASS6 binding to APC/C E3 ubiquitin-protein ligase complex/FZR1.
Synonyms: CCDC84; DLNB14; MVA4
Tractability: Small molecule: a structure with a bound ligand is known.
Gene: Protein-coding gene on chromosome 11 (118,998,138 to 119,015,793, forward strand). Ensembl gene ENSG00000186166.
Subcellular location: Cytoplasm, cytoskeleton, microtubule organizing center, centrosome
Subcellular location (Human Protein Atlas): Nucleoplasm
Gene Ontology:
Molecular function: protein binding
Biological process: chromosome separation; mRNA splicing, via spliceosome; negative regulation of centrosome duplication; regulation of protein catabolic process; spliceosomal tri-snRNP complex assembly; spliceosome conformational change to release U4 (or U4atac) and U1 (or U11)
Cellular component: centrosome; U12-type precatalytic spliceosome; U4atac/U6atac x U5 tri-snRNP complex
Genetic constraint (gnomAD): Loss-of-function variants: 51 observed, 52.49 expected, observed/expected ratio (o/e) 0.97, 90% interval 0.77 to 1.23. The upper end of that interval is the gene's LOEUF score, 1.23, which puts it in group 5 of 6, group 1 being the genes least tolerant of losing a copy. Missense variants: 467 observed, 419.41 expected, observed/expected ratio (o/e) 1.11, 90% interval 1.03 to 1.2. Synonymous variants: 156 observed, 146.71 expected, observed/expected ratio (o/e) 1.06, 90% interval 0.93 to 1.21.
Homologues: Orthologues: chimpanzee CENATAC (99% identical), macaque CENATAC (89% identical), pig CENATAC (89% identical), dog CENATAC (89% identical), guinea pig CENATAC (86% identical), mouse Cenatac (86% identical), rat Cenatac (85% identical), rabbit CENATAC (84% identical), tropical clawed frog cenatac (51% identical), zebrafish cenatac (45% identical).